AOC3 (amine oxidase copper containing 3)
Diseases named in the same sentence as AOC3 in open-access papers (continued):
Sharing a sentence is not in itself a finding about the gene and the disease.
glioma (2 papers, 2020 to 2023). A benign or malignant brain and spinal cord tumor that arises from glial cells (astrocytes, oligodendrocytes, ependymal cells). "Further, the association between AOC3 gene expression and clinical characteristics in glioma subgroups was observed by chi-square test and performed by box and whisker plots." (PMID 32349342, 2020). "AOC3 as a valid prognostic marker for human glioma was displayed by Kaplan–Meier plots (exon, p = 0.0283; methylation, p < 0.0001)." (PMID 32349342, 2020). "An in-depth analysis of AOC3 (VAP-1) gene expression was performed using 695 glioma samples derived from the cancer genome atlas (TCGA)-lower grade glioma and glioblastoma (GBMLGG) cohort." (PMID 32349342, 2020). "In this study, a powerful confirmation of the prognostic potential of AOC3 gene expression was illustrated from the 695 glioma samples that were derived from TCGA-LGGGBM cohort." (PMID 32349342, 2020). "Analyses of AOC3 exon expression and DNA methylation in glioma subgroups were conducted using UCSC Xena." (PMID 32349342, 2020). "We preliminarily investigated AOC3 gene expression and methylation status in the glioma subgroups and downloaded the level 3 data from UCSC Xena." (PMID 32349342, 2020). "The potential value of AOC3 gene expression in the prognosis evaluation in gliomas was validated by 529 LGG cases and 166 GB cases available from the exon expression and by the DNA methylation datasets." (PMID 32349342, 2020). "AOC3 gene expression positively correlated with grade, recurrence, and patient survival in gliomas, but the DNA methylation status was inversely related to disease progression and outcomes in this tumor." (PMID 32349342, 2020). "Low levels of DNA methylation occurred in worse prognostic glioma, which might imply demethylation as an epigenetic modification to enhance gene expression in accordance with high levels of AOC3 gene expression in patients with poor outcome." (PMID 32349342, 2020). "However, lower DNA methylation status of AOC3 showed worse prognosis for glioma patients (all p < 0.0001)." (PMID 32349342, 2020). "Publicly available large-scale database and clinical parameters derived from TCGA lower grade glioma and glioblastoma (GBMLGG) cohort were used to assess AOC3 gene expression in different grades of gliomas." (PMID 32349342, 2020). "AOC3 gene expression positively correlated with high WHO grade, recurrence, and worse survival in glioma subgroups (p = 0.0081, p = 0.0117, and p = 0.0216 respectively)." (PMID 32349342, 2020).
Hepatic steatosis (2 papers, 2020 to 2021). Steatosis is a term used to denote lipid accumulation within hepatocytes. "Both resulted in fat accretion, especially in the SCWAT, rich in AOC3 activity in the db-/- littermates, without worsening hepatic steatosis since liver possess a lower AOC3 activity than WAT." (PMID 34444782, 2021).
Insulin resistance (2 papers, 2012 to 2020). Increased resistance towards insulin, that is, diminished effectiveness of insulin in reducing blood glucose levels. "In addition, AOC3 activity is thought to ameliorate insulin resistance and is implicated in insulin signaling." (PMID 22238597, 2012).
autosomal dominant cutis laxa (1 paper, 2024). Autosomal dominant cutis laxa (ADCL) is a connective tissue disorder characterized by wrinkled, redundant and sagging inelastic skin associated in some cases with internal organ involvement. "MYH11 and SYNPO2 linked to EMILIN1-related Connective Tissue Disease, AOC3 and MYH11 linked to Autosomal Dominant Cutis Laxa, MYH11 and SYNPO2 linked to Lethal Arteriopathy Syndrome due to Fibulin-4 Deficiency, while AOC3 and TAGLN linked to Renal Tubular Dysgenesis of Genetic Origin." (PMID 39480826, 2024). "We propose that AOC3 and MYH11 are novel genes in Autosomal Dominant Cutis Laxa." (PMID 39480826, 2024).
Cachexia (1 paper, 2020). Severe weight loss, wasting of muscle, loss of appetite, and general debility related to a chronic disease. "The newly identified protein interaction between AOC3 and ZAG highlights a previously unknown functional relationship, which may be relevant to inflammation, energy metabolism and the development of cachexia." (PMID 32315567, 2020).
invasive carcinoma (1 paper, 2017). A carcinoma that is not confined to the epithelium, and has spread to the surrounding stroma. "The results corroborated previous reports of higher levels of cofilin-1 and p23 and lower levels of membrane copper amine oxidase (AOC-3) in invasive carcinoma patients when compared to normal controls." (PMID 28265552, 2017).
osteosarcoma (1 paper, 2022). A usually aggressive malignant bone-forming mesenchymal neoplasm, predominantly affecting adolescents and young adults. "Therefore, our study indicates that the resting dendritic cell signature constructed by AOC3, CDK6, COL22A1, and RNASE6 may contribute to predicting osteosarcoma prognosis and thus therapy guidance." (PMID 36189307, 2022).
ureteric obstruction (1 paper, 2020). "Treatment with the AOC3 inhibitor semicarbazide significantly reduced kidney fibrosis in a unilateral ureteric obstruction model in mice." (PMID 32315567, 2020).
tumor (32 papers, 2012 to 2025). "As an endothelial adhesion molecule, AOC3 has previously been implicated to play a role in lymphocyte-endothelial interactions to promote tumor growth." (PMID 38461356, 2024). "Differential expression analysis and ceRNA network analysis showed several tumor-associated transcripts (Dock4, Fmr1, Zfhx3, Ralb, Mll, Aoc3, and circHRH4) may involve in ALV-J-induced tumorigenesis." (PMID 30286182, 2018). "The expression of COX11, COX17, LIAS, CDKN2A and AOC3 was significantly higher in tumor tissues than in normal tissues." (PMID 38078879, 2023). "MAOA (T; p = 0.005) and MAOB (T; p = 0.006) in tumor cells were higher in ACN, whereas LOX was higher in tumor cells (T; p < 0.001) and LOX in stromal cells (S; p < 0.001) and AOC3 in tumor cells (T; p < 0.001) were higher in PCC." (PMID 37509535, 2023). "AOC3 is an endothelial adhesion protein that is involved in tumor cell extravasation and can mediate tumor infiltration into lymphocytes and invasion into the endothelial cell layer of other organs and tissues." (PMID 37251946, 2023). "Serum AOC3 promotes lymphocyte binding in endothelial cells and can lead to lymphocyte accumulation in tumor vesicles." (PMID 29261141, 2017). "In addition, the stromal cell expressing AOC3 influences tumor biology." (PMID 29261141, 2017). "Other proteins were inversely correlated to tumor tissue content, the most significant being; TENX, EHD2, ZA2G, AOC3, FETUA and THRB." (PMID 28445515, 2017). "Notably, AOC3, F8, and IL1A were found to be highly expressed in the normal group, while COA6, FKBP4, and LOXL2 were highly expressed in the tumours." (PMID 38577594, 2024).
cancer (20 papers, 2013 to 2025). A tumor composed of atypical neoplastic, often pleomorphic cells that invade other tissues. "AOC3 has been reported to mediate the adhesion of lymphocytes infiltrating around tumors to various cancerous tissues, killing cancer cells and thus exerting an inhibitory effect on tumors." (PMID 40496615, 2025). "AOC3 negativity was associated with short DFS and OS in PR-positive cancer (p = 0.028 and p = 0.012, respectively)." (PMID 29261141, 2017). "AOC3 is an endothelial adhesion protein, and is involved in cancer cell extravasation of cells that invade the endothelial cell layer of other organs and tissues, and AOC3 is reported to be associated with poor prognosis." (PMID 29261141, 2017). "Some amine oxidases have been reported to be involved in regulating cancers; LOX has played an important role in colorectal cancer cell dissemination in the bone marrow, and expression of AOC3 is associated with cancer prognosis in various tumors." (PMID 29261141, 2017). "AOC3 is dysregulated in various cancers, with contradictory roles." (PMID 36189307, 2022). "Thus, autophagy may be another mechanism linking AOC3 and cancer progression." (PMID 38461356, 2024). "AOC3 is a marker to determine the myofibroblast phenotype of CAF, and the myofibroblast promotes cancer cell migration and invasion." (PMID 29261141, 2017). "Glycosylation of HMGCS1 and AOC3 proteins have not been reported in any cancer types." (PMID 35752862, 2022).
inflammation (4 papers, 2016 to 2024). Aberrant reaction of the microcirculation characterized by movement of fluid and leukocytes from the blood into extravascular tissues. "AOC3/VAP-1 participates in developing pulmonary inflammation and fibrosis by regulating the accumulation of pathogenic leukocyte subtypes." (PMID 34869715, 2021).
cardiac diseases (2 papers, 2021 to 2023). "Examples of drug targets for cardiac diseases detected in primary cardiac fibroblasts but not in hPSC-CFs include AOC3 (hydralazine) and NPR2 (nesiritide)." (PMID 36950336, 2023).
AOC3 also shares sentences with these, for which no sentence is quoted: infection (10 papers); Hypertension (8); liver fibrosis (8); type 2 diabetes (8); diabetic nephropathy (7); diabetic retinopathy (7); psoriasis (7); cardiovascular disease (6); melanoma (6); primary sclerosing cholangitis (6); rheumatoid arthritis (6); cyst (5); heart failure (5); inflammatory bowel disease (5); Stroke (5); Alzheimer disease (4); Cirrhosis (4); coronary artery disease (4); COVID-19 (4); hepatocellular carcinoma (4); Hyperglycemia (4); viral infection (4); end-stage renal disease (3); liver cancer (3); liver cirrhosis (3); prostate carcinoma (3); Sepsis (3); uveitis (3); acute myocardial infarction (2); acute myocarditis (2).
A further 95 diseases each share a sentence with AOC3 in 2 papers or fewer.